CAPN8 (calpain 8)
Description:
Calcium-regulated non-lysosomal thiol-protease. Involved in membrane trafficking in the gastric surface mucus cells (pit cells) and may involve the membrane trafficking of mucus cells via interactions with coat protein. Proteolytically cleaves the beta-subunit of coatomer complex (By similarity).
Synonyms: nCL-2
Tractability: No criterion of Open Targets' tractability assessment is met for any kind of drug.
Gene: Protein-coding gene on chromosome 1 (223,538,007 to 223,665,723, reverse strand). Ensembl gene ENSG00000203697.
Subcellular location: Cytoplasm; Golgi apparatus
Subcellular location (Human Protein Atlas): Nuclear membrane; Nucleoplasm; Vesicles
Pathways (Reactome):
Extracellular matrix organization: Degradation of the extracellular matrix
Gene Ontology:
Molecular function: calcium-dependent cysteine-type endopeptidase activity; calcium ion binding
Biological process: proteolysis
Cellular component: cytoplasm; Golgi apparatus
Genetic constraint (gnomAD): Loss-of-function variants: 73 observed, 74.9 expected, observed/expected ratio (o/e) 0.97, 90% interval 0.81 to 1.18. The upper end of that interval is the gene's LOEUF score, 1.18, which puts it in group 5 of 6, group 1 being the genes least tolerant of losing a copy. Missense variants: 684 observed, 671.25 expected, observed/expected ratio (o/e) 1.02, 90% interval 0.96 to 1.09. Synonymous variants: 272 observed, 259.62 expected, observed/expected ratio (o/e) 1.05, 90% interval 0.95 to 1.16.
Homologues: Orthologues: chimpanzee CAPN8 (99% identical), macaque CAPN8 (96% identical), rat Capn8 (85% identical), mouse Capn8 (83% identical), pig CAPN8 (83% identical), dog CAPN8 (77% identical), rabbit CAPN8 (73% identical), tropical clawed frog capn8 (62% identical), Drosophila melanogaster CalpB (45% identical), Caenorhabditis elegans clp-1 (35% identical), Caenorhabditis elegans clp-7 (34% identical), Caenorhabditis elegans clp-6 (33% identical), and 6 more. Paralogues in human: CAPN2 (61% identical), CAPN1 (59% identical), CAPN11 (50% identical), CAPN3 (49% identical), CAPN9 (48% identical), CAPN12 (43% identical), CAPN14 (37% identical), CAPN13 (32% identical), CAPN5 (31% identical), CAPN6 (27% identical), CAPN10 (25% identical), CAPN7 (24% identical), and 8 more.
Diseases named in the same sentence as CAPN8 in open-access papers:
CAPN8 is named in the same sentence as 26 diseases in open-access papers, as found by Europe PMC text mining. Sharing a sentence is not in itself a finding about the gene and the disease. The quoted sentences say what the papers report.
gastric cancer (2 papers, 2016 to 2022). A primary or metastatic malignant neoplasm involving the stomach. "Consistent with our studies, CAPN8 was claimed to be a potential oncogene in gastric cancer, hepatic carcinoma, and lung cancer, causing the occurrence of precancerous lesions and cancer progression." (PMID 36389799, 2022). "CCK-8 assay revealed that cell viability was reduced in calpain-9-transfected gastric cancer cells, while calpain-8 overexpression had little effect on cell viability." (PMID 27404891, 2016). "We next investigated the protein expression of calpain-8 and calpain-9 in 22 paired gastric cancer samples." (PMID 27404891, 2016). "We next determined the effects of calpain-8 and calpain-9 on cellular apoptosis in gastric cancer cells." (PMID 27404891, 2016). "Nevertheless, the relative mRNA expression of calpain-8 was reduced in gastric cancer from the GSE13911 dataset, whereas its mRNA levels were increased in gastric cancer from the TCGA-STAD dataset." (PMID 27404891, 2016). "However, the protein levels of calpain-8 in gastric cancer cell lines were comparable with that in GES-1 cells." (PMID 27404891, 2016). "In this study, we examined the potential effects of calpain-8 and calpain-9 on tumor growth in vitro and in vivo, and we also determined the clinical significance of calpain-9 expression as well as its correlation with gastric cancer progression." (PMID 27404891, 2016). "The changes of calpain-8 mRNA levels in different gastric cancer cell lines were also discordant." (PMID 27404891, 2016). "Therefore, the role of calpain-8 in gastric cancer needs to be clarified in further research." (PMID 27404891, 2016). "We also examined the expression of calpain-8 and calpain-9 in normalized gastric mucosa cell line GES-1 and various gastric cancer cell lines (AGS, MGC80-3, BGC-823, HGC-27, MKN-28, MKN-45, and SGC-7901)." (PMID 27404891, 2016). "To understand whether calpain-8 and calpain-9 were involved in gastric carcinogenesis, we first screened differentially expressed genes and examined the mRNA expression patterns of calpain family in gastric cancer tissues from reported GEO13 and TCGA-STAD14 datasets." (PMID 27404891, 2016). "Herein, we demonstrated that calpain-9 was generally decreased in gastric cancer cell lines and primary tumor tissues, while calpain-8 expression was not significantly altered." (PMID 27404891, 2016). "Annexin V staining revealed that overexpression of calpain-9, but not calpain-8, significantly increased cell apoptosis in both gastric cancer cell lines." (PMID 27404891, 2016). "Western blot analysis revealed that calpain-9 protein levels were down-regulated in gastric cancer compared with matched adjacent normal gastric mucosa, while calpain-8 protein levels were not significantly altered." (PMID 27404891, 2016). "Immunohistochemical (IHC) assay also confirmed that the protein expression of calpain-9, but not calpain-8, was decreased in gastric cancer samples." (PMID 27404891, 2016). "Western blot analysis revealed that transfection with calpain-9, but not calpain-8, enhanced the cleavage of caspase-12 in both gastric cancer cell lines." (PMID 27404891, 2016). "Because calpain-9, but not calpain-8, was decreased in gastric cancer and displayed anti-tumorigenic effects in vitro and in vivo, we next determined the correlations between calpain-9 expression and clinicopathological features in 151 gastric cancer samples." (PMID 27404891, 2016).
lung adenocarcinoma (2 papers, 2020 to 2022). A carcinoma that arises from the lung and is characterized by the presence of malignant glandular epithelial cells. "The present study uncovered that high expression of IRX2, SPINK13, and CAPN8 could facilitate tumor progression in LUAD with multiple lung adenocarcinoma cell lines." (PMID 35102706, 2022). "Our results signaled that IRX2, SPINK13, and CAPN8 could serve as novel therapeutic targets to prevent tumor growth in lung adenocarcinoma." (PMID 35102706, 2022). "In lung adenocarcinoma, our results showed that smoking increased the expression of three genes, AHRR, GPR15, and HDGF, and decreased the expression of two genes, CAPN8, and RPS6KA1, which were consequently associated with increased smoking-related mutational signature." (PMID 32928150, 2020). "Our results showed three additional genes, CAPN8, HDGF and RPS6KA1, may be involved in smoking-related mutational signature, mediated by gene expression altered by tobacco smoking in lung adenocarcinoma." (PMID 32928150, 2020). "For lung adenocarcinoma, we found that the expression levels of three genes, GPR15, HDGF, and AHHR, were associated with increased smoking-related mutational signature, while an inverse association was observed for the other four genes, NWD1, KCNQ1, CAPN8 and RPS6KA1." (PMID 32928150, 2020). "CAPN8, IRX2, and SPINK13 may serve as novel targets of targeted and immune‐based therapies in lung adenocarcinoma." (PMID 35102706, 2022).
lung carcinoma (2 papers, 2020 to 2022). "CAPN8 has been proved up-regulated in lung cancer and could be a prognostic biomarker." (PMID 32411535, 2020).
thyroid cancer (2 papers, 2022). "Firstly, we explored the expression and downstream signaling pathways of CAPN8 in The Cancer Genome Atlas—Thyroid Cancer (TCGA-THCA) cohort and in vitro tumor tissues." (PMID 36389799, 2022). "CAPN8 showed a substantial rise in protein, mRNA, and relative IHC score (D) in thyroid cancer tissues." (PMID 36389799, 2022). "Hereby we hypothesize that CAPN8 might facilitate the metastasis of thyroid cancer cells and lead to poor prognosis by inducing an inhibitory TIME pattern." (PMID 36389799, 2022). "It is our study that collects LRRN4CL, HS3ST3A1, PCOLCE2, and CAPN8 all together for the first time and sets them as biomarkers related to TME in thyroid cancer, which might become potential candidate targets for TC immunotherapy." (PMID 36590308, 2022). "Furthermore, HS3ST3A1 and CAPN8 were highly expressed in thyroid tumor tissue, especially in tumors with LNM, and their downregulation can inhibit the proliferation and invasion of thyroid cancer cells." (PMID 36590308, 2022).
gastropathies (1 paper, 2010). "Here we report that two gastrointestinal-tract-specific calpains, calpain 8/nCL-2 and calpain 9/nCL-4, are involved in the mucosal defense against stress-induced gastropathies." (PMID 20686710, 2010). "Our results also identify CAPN8 and CAPN9 as promising targets for various stress-induced human gastropathies." (PMID 20686710, 2010).
Obesity (1 paper, 2021). Accumulation of substantial excess body fat. "No role in regulating metabolism or obesity has been discovered previously for either calpA/CAPN8 or sdk/SDK1." (PMID 34748544, 2021).
papillary thyroid cancer (1 paper, 2022). "In vitro, the downregulation of HS3ST3A1 and CAPN8 presented the inhibition of proliferation and invasion in papillary thyroid cancer cells." (PMID 36590308, 2022). "To verify the cellular function of HS3ST3A1 and CAPN8, we transfected shHS3ST3A1 and shCAPN8 into papillary thyroid cancer cells BCPAP and TPC-1, which downregulation was detected by Western blot." (PMID 36590308, 2022).
tumor (9 papers, 2015 to 2025). "In particular, the effect of CAPN8 on the tumor immune microenvironment (TIME) and immunotherapy response is unclear." (PMID 36389799, 2022). "CAPN8 was found to be a significant risk factor for THCA with a markedly elevated level of mRNA and protein in tumor tissues." (PMID 36389799, 2022). "Firstly, CAPN8 was found to be a significant risk factor for THCA with a markedly elevated level of mRNA and protein in tumor tissues." (PMID 36389799, 2022). "Three genes in the model, IRX2, SPINK13, and CAPN8, were also validated with their expression and potentials in tumor proliferation." (PMID 35102706, 2022). "RT-qPCR results indicated that the mRNA levels of HS3ST3A1 and CAPN8 were remarkably higher in tumor tissues compared with normal tissues." (PMID 36590308, 2022). "In particular, the effect of CAPN8 on the tumor immune microenvironment (TIME), which is a well-recognized factor in promoting the metastasis of THCA, is unclear." (PMID 36389799, 2022). "Firstly, the expression and the prognostic value of CAPN8 were explored in public datasets and in vitro tumor tissues." (PMID 36389799, 2022). "Collectively, the expression status of IRX2, SPINK13, and CAPN8 was in line with our findings in scRNA‐seq that they all showed an elevation both in tumor tissues and cells, which was also coincided with the development of tumor stage in LUAD." (PMID 35102706, 2022). "Clinical specimens were collected and subjected to RT-qPCR and IHC staining, which showed higher HS3ST3A1 and CAPN8 expression levels in tumor tissues, especially in tumors with LNM." (PMID 36590308, 2022). "We found that tumor size and weight were significantly suppressed in the calpain-9 group, compared with those in the calpain-8 group and control group." (PMID 27404891, 2016). "Three immune subtypes were identified with quite different patterns of prognosis, immunotherapy response, and drug sensitivity, providing novel insights for the treatment of THCA and helping understand the cross-talk between CAPN8 and tumor immune microenvironment." (PMID 36389799, 2022). "Moreover, we found that IRX2, SPINK13, and CAPN8 showed great superiority to their counterparts in differentiation, especially in the ability to distinguish malignant tumor cells from normal epithelial cells." (PMID 35102706, 2022). "Our results signaled that IRX2, SPINK13, and CAPN8 could serve as novel therapeutic targets to prevent tumor growth in LUAD." (PMID 35102706, 2022). "Additionally, the malignancy behaviors of HS3ST3A1 and CAPN8 in the tumor process were verified through tissue and cellular experiments." (PMID 36590308, 2022). "The Wilcoxon rank-sum test indicated the expression levels of 4 DEGs among normal and tumor tissue in paired or unpaired samples, which indicated HS3ST3A1 and CAPN8 expressed significantly higher in tumor tissues, while the other two genes, LRRN4CL and PCOLCE2, were not." (PMID 36590308, 2022). "Calpain-9, but not calpain-8, induced cell cycle arrest in the G1 phase and cellular apoptosis in vitro, and it attenuated the growth of subcutaneous tumor xenografts in vivo." (PMID 27404891, 2016). "Nevertheless, in transformed gastric mucosa, calpain-9, but not calpain-8, might function as a tumor suppressor through proliferation suppression and apoptosis induction." (PMID 27404891, 2016). "Interestingly, five genes (CDC45, KIF13B, ORC6, SHCBP1,and CAPN8) were not present in previously reported molecular tumor grading signatures." (PMID 26474389, 2015).
cancer (7 papers, 2019 to 2025). A tumor composed of atypical neoplastic, often pleomorphic cells that invade other tissues. "Six and eight CAPN8-related cancer hallmarks were screened out by the adaptive LASSO regression and random survival forest algorithm, respectively." (PMID 36389799, 2022). "In terms of the 50 cancer hallmarks, interferon-gamma response, inflammatory response, E2F-targets, etc., were significantly upregulated in the CAPN8-high group, while the oxidative phosphorylation pathway was slightly downregulated." (PMID 36389799, 2022).
CAPN8 also shares sentences with these, for which no sentence is quoted: Ataxia (2 papers); adenoma (1); Batten disease (1); Brain atrophy (1); breast carcinoma (1); epilepsy (1); gastric tumor (1); Global developmental delay (1); hepatic carcinoma (1); Leigh disease (1); lung squamous cell carcinoma (1); lymph node metastasis (1); Progressive myoclonic epilepsy (1); Retinal atrophy (1); Spastic paraplegia (1); speech delays (1); thyroid tumor (1).